LINC02099 (long independently transcribed non-coding RNA 2099)
Synonyms: Slt; AC145110.1
Gene: Long non-coding RNA gene on chromosome 8 (29,748,309 to 29,798,492, forward strand). Ensembl gene ENSG00000253490.
Diseases named in the same sentence as LINC02099 in open-access papers:
LINC02099 is named in the same sentence as 2 diseases in open-access papers, as found by Europe PMC text mining. Sharing a sentence is not in itself a finding about the gene and the disease.
LINC02099 shares sentences with these, for which no sentence is quoted: breast carcinoma (1 paper); tumor (1).